INS (insulin)
Diseases named in the same sentence as INS in open-access papers (continued):
Sharing a sentence is not in itself a finding about the gene and the disease.
Insulin resistance (continued). "According to the longitudinal epidemiological studies, there have been elevated plasma insulin levels in AD patients, with a close association between cognitive disorder and insulin resistance in T2DM patients." (PMID 39626951, 2024). "Microbiome profile scores developed with 32 (EDIH) and 15 (EDIP) genera were associated with higher insulin and homeostatic model assessment of insulin resistance." (PMID 39703541, 2024). "In the early stage of diabetes, insulin resistance is associated with impaired glucose-uptake into cells and with pancreatic β-cell compensatory responses, including increased insulin biosynthesis and secretion." (PMID 39599757, 2024). "In this sense, insulin resistance causes abnormalities in lipid storage and lipolysis in insulin-sensitive tissues, which can increase the flow of free fatty acids from adipose tissue to the liver and, consequently, cause steatosis." (PMID 38612504, 2024). "OVA subjects have impaired insulin secretion and increased insulin resistance associated with maternal age and obesity, as in GDM, but these defects are milder in OVA subjects." (PMID 38833438, 2024). "In the context of obesity, the interaction of insulin signalling pathways with other pathways causes dysfunction in insulin signalling and increased insulin resistance." (PMID 38164186, 2024). "Breastfeeding was associated with higher insulin resistance-adjusted insulin secretion (Insulin Secretion-Sensitivity Index-2) in the unadjusted analyses only." (PMID 38772880, 2024). "Peripheral insulin resistance causes pancreatic β cells to secrete more insulin, a process known as compensatory hyperinsulinemia." (PMID 39458933, 2024). "Adipose tissue is a major insulin target, and impaired glucose uptake in adipose tissue is linked to insulin resistance." (PMID 38659573, 2024). "This reduction was associated with elevated fasting insulin and glucose levels, underscoring the role of NO in metabolic regulation and its potential as a biomarker for insulin resistance in PCOS." (PMID 39968366, 2024). "In contrast, a study investigating specific genetic variations in the IL6 promoter, including − 174 G/C and − 572 G/C polymorphisms, found associations with insulin resistance, dyslipidemia, and increased serum insulin release." (PMID 38388670, 2024). "Ceramide can affect insulin-stimulated Akt activation and subsequent glucose uptake in the liver and skeletal muscle, which is another cause of insulin resistance." (PMID 38256005, 2024). "It has been shown that people diagnosed with type 2 diabetes had lower UIC compared to the control groups and that the UICs were inversely linked with the plasma insulin levels and the Homeostatic Model Assessment of Insulin Resistance (HOMA-IR) index." (PMID 39212589, 2024). "Type 1 diabetes is characterized by deficient insulin secretion, while type 2 diabetes results from severe insulin resistance due to receptor dysfunction or subsequent signaling abnormalities." (PMID 38626157, 2024). "Another study showed that P4 treatment caused mild insulin resistance together with a depletion of pancreatic insulin stores in the long run." (PMID 38539988, 2024). "The dysfunction of phospholipid metabolism enzymes and the change in membrane phospholipid composition are associated with insulin resistance, indicating that phospholipids play an important role in the regulation of insulin sensitivity." (PMID 38674894, 2024). "Iron-related oxidative processes and ROS accumulation in pancreatic β-cells are closely associated with insulin resistance and insufficient insulin secretion, leading to the pathogenesis of T2DM." (PMID 38693581, 2024). "Loss of PPARγ function has been shown to promote insulin resistance, suggesting a critical role for PPARγ in insulin signalling associated with adipose tissue metabolism." (PMID 38874666, 2024).
Insulin resistance (continued). "Cluster 1 in adipose tissue was enriched in insulin stimulus-related pathways, further suggesting a possible association between adipose deposition in Eastern pigs and insulin resistance." (PMID 38474122, 2024). "On the other hand, elevated serum levels of irisin, an important regulator of insulin signaling, have been associated with increased ER (endoplasmic reticulum) stress leading to insulin resistance." (PMID 38431555, 2024). "Weight gain, especially abdominal obesity, is linked to insulin resistance, a condition in which cells lose their sensitivity to the physiological actions of insulin, resulting in hyperglycaemia." (PMID 39639395, 2024). "Type 2 diabetes (T2D) is caused by a combination of insulin resistance and an inability of pancreatic β-cells to produce sufficient insulin." (PMID 39337631, 2024). "Insulin resistance (IR) is characterized by the reduced body's cells’ response to insulin and is a significant risk factor for cardiovascular disease (CVD), independent of diabetes." (PMID 39630767, 2024). "Specifically, myocardial insulin resistance is associated with impaired insulin-mediated glucose uptake, reduced mitochondrial oxidative capacity, and a decreased Glut4 content." (PMID 39026321, 2024). "As a result, insulin resistance induced by glucocorticoids is linked to suppressing insulin signaling pathways, such as the PKB/AKT and PI3K/mTOR pathways, in mammals." (PMID 39339244, 2024). "Through the Randle cycle, a high-fat regime causes insulin resistance, which hinders the transfer of insulin-stimulated glucose and lowers beta-cell activity." (PMID 38926327, 2024). "Type 2 diabetes (T2D) is a chronic metabolic disorder caused by defective insulin signaling, insulin resistance, and impairment of insulin secretion." (PMID 39676616, 2024). "Studies have highlighted the significance of the IRS1 gene in insulin signaling, with genetic variations linked to insulin resistance, a pivotal factor in GDM development." (PMID 38694942, 2024). "Obesity is a significant risk factor for insulin resistance, a maladaptive metabolic state characterized by impaired insulin-mediated glucose uptake, changes in insulin secretion and dyslipidemia." (PMID 39188529, 2024). "Recent studies have reported that insulin resistance is primarily caused by the inability of insulin to effectively activate the insulin receptor substrate (IRS)." (PMID 38818523, 2024). "Ectopic fat depositions in the liver cause hepatic insulin resistance and decrease hepatic insulin clearance." (PMID 39769002, 2024). "Mature adipocytes are insulin sensitive, and inflammation-induced adipocyte dedifferentiation causes insulin resistance." (PMID 39339785, 2024). "Suggesting, that the overall diminished performance in global function and WM in our insulin-resistant group was most likely a result of IR-related mechanistic pathways (i.e. brain insulin resistance, inflammation, oxidative stress) caused by glycemic changes." (PMID 39261457, 2024). "Smoking has been linked to insulin resistance, and nicotine is associated with decreased insulin sensitivity." (PMID 39518747, 2024). "Insulin resistance is associated with increased release of circulating free fatty acids (FFAs) from adipose tissue, which inhibit insulin-mediated glucose uptake in muscle, leading to hyperglycemia and hyperinsulinemia." (PMID 39728298, 2024). "It modulates the metabolic actions of insulin, and its mutation has been associated with insulin resistance." (PMID 39684610, 2024). "Insulin resistance is also associated with impaired stimulation of glycogen synthesis induced by insulin." (PMID 38397072, 2024). "EP has also been shown to enhance β‐cell function, increase insulin sensitivity, and improve insulin resistance caused by diabetes, as evidenced by a remarkable increase in HOMA‐β, ISI, and a decrease in HOMA‐IR." (PMID 38873458, 2024).
Insulin resistance (continued). "Such hyperglycemic effects are often caused by insulin resistance, which reduces insulin-stimulated glucose uptake into tissues." (PMID 39033139, 2024). "We demonstrate that Lyz-IFNγR2−/− mice are protected from diet-induced insulin resistance despite developing fatty liver, and this is associated with improved insulin signaling in the liver." (PMID 38951527, 2024). "Liver-specific knockout of Mfn2 causes excessive mitochondrial fission, reduces insulin signal transduction in muscle and liver tissues, and induces susceptibility to insulin resistance (IR)." (PMID 38542170, 2024). "We found that higher insulin and insulin resistance associated statistically significantly with smaller hippocampal tail volume in FEP at one-year follow-up." (PMID 39085221, 2024). "The immune system attacks and damages the pancreatic beta cells that produce insulin in type 1 autoimmune disease and type 2, which is mainly caused by insulin resistance and is typically linked to obesity and lifestyle factors." (PMID 39493064, 2024). "Insulin resistance refers to the weakening of the physiological role of insulin in the body, and obesity is often the main cause of insulin resistance, which in turn will put obese people in a state of chronic inflammation." (PMID 39055491, 2024). "The increase in ANGPTL8 synthesis was ascribed to albumin loss, a condition that leads to insulin resistance and heightened insulin requirements in individuals with T2D and albuminuria." (PMID 38790911, 2024). "Obesity-mediated liver inflammation is also attenuated in Lyz-IFNγR2−/− mice with profoundly reduced intrahepatic levels of IL-12, and in vivo treatment with IL-12 causes insulin resistance by impairing hepatic insulin signaling in wild-type (WT) mice." (PMID 38951527, 2024). "Type 2 diabetes is typically associated with insulin secretion defects, insulin resistance, and the death of pancreatic β cells." (PMID 39238846, 2024). "Since skeletal muscle is the principal site of insulin-stimulated glucose uptake, it is also considered to be the main cause of whole-body insulin resistance." (PMID 39095777, 2024). "T2DM is characterized by the progressive loss of insulin secretion in the context of insulin resistance." (PMID 38693581, 2024). "Obesity causes insulin resistance (IR), and the resulting accumulation of insulin promotes fat synthesis, thus establishing a vicious cycle." (PMID 38678275, 2024). "Previous studies have highlighted significant differences between women and men regarding insulin action, susceptibility to insulin resistance development, and response to factors influencing insulin sensitivity." (PMID 39410926, 2024). "Defects in the insulin signaling cascade have been associated with severe insulin resistance and T2D." (PMID 39594636, 2024). "Glucose-tolerance tests (GTTs) and insulin-tolerance tests (ITTs) revealed that Nrg4 deficiency exacerbated glucose intolerance and insulin resistance following HFD feeding at lower housing temperatures." (PMID 38015639, 2024). "Defects in the PI3 kinase signaling pathway have been implicated in the etiology of insulin resistance, ultimately leading to increased insulin levels in an attempt to overcome decreased intracellular signaling." (PMID 40808720, 2024). "Insulin resistance refers to a reduced biological response of cells and tissues to insulin and is considered to be a causal link between adiposity and type 2 diabetes." (PMID 39335757, 2024). "Type 1 DM results from an autoimmune response that causes a decrease in insulin secretion, while type 2 DM stems from insulin resistance with eventual impaired insulin function." (PMID 39449925, 2024). "Rapamycin negatively affects glucose tolerance by inhibiting insulin production and secretion from pancreatic beta-cells and by causing hepatic insulin resistance." (PMID 38360109, 2024).
Insulin resistance (continued). "Insulin resistance is present throughout the MetS, and hyperinsulinemia triggered by compensatory increase in insulin is another important cause of induced hypertension." (PMID 39179999, 2024). "The insulin secretion during pregnancy is often severely limited, and impaired glucose tolerance is associated with β-cell dysfunction and insulin resistance." (PMID 39216124, 2024). "T2D is identified by a progressive loss of insulin secretion and impaired insulin sensitivity, referred to as insulin resistance." (PMID 39872377, 2024). "Several authors suggest that glucotoxicity causes an increase in neuronal insulin resistance, impaired insulin signaling, a pro-inflammatory state, mitochondrial dysfunction, and vascular damage, leading to the deposition of β-amyloid and tau protein." (PMID 39335505, 2024). "Insulin resistance in adipose tissue, caused by inflammation, obstructs insulin’s effect on lipolysis." (PMID 39328456, 2024). "Hyperglycemia can be caused by abnormalities in insulin secretion or decreased insulin action due to insulin resistance." (PMID 39484071, 2024). "Increased levels of circulating insulin (here referred to as Hyperin) secondary to insulin resistance (IR) represent a condition that predisposes to many diseases." (PMID 39457728, 2024). "According to this paradigm, reduced hepatic insulin clearance causes secondary hepatic insulin resistance and steatosis." (PMID 39640841, 2024). "Lipidolysis in late pregnancy promotes elevated NEFA, which is associated with insulin response and peripheral insulin resistance, and ketogenesis is the result of reduced glucose and insulin concentrations." (PMID 39397808, 2024). "Insulin resistance, characterized by decreased cellular responsiveness to insulin signaling, is a hallmark of type 2 diabetes." (PMID 39741509, 2024). "Increased TNF-α levels have also been demonstrated to cause insulin resistance by affecting insulin signaling and glucose absorption in vivo, similarly to IL-6." (PMID 38390960, 2024). "Two pathways related to sugar degradation were more abundant in patients before treatment, possibly correlated with disorders of sugar metabolism and risk factors, such as hyperglycemia, insulin resistance, and insufficient insulin secretion." (PMID 39035441, 2024). "Maternal insulin concentrations, insulin resistance, β-cell function, and insulin sensitivity were associated with moderate changes in the methylation of CpGs." (PMID 38254965, 2024). "Obesity-associated inflammation is a suggested causal link to insulin resistance, as inflammatory cytokines have been shown to interfere with myocyte insulin signaling." (PMID 38999834, 2024). "The root cause of type 2 diabetes (T2D) is insulin resistance (IR), defined by the failure of cells to respond to circulating insulin to maintain lipid and glucose homeostasis." (PMID 38967989, 2024). "A pathophysiological hallmark of T2D is insulin resistance, a metabolic derangement characterized by the diminished ability of cells to respond to insulin, primarily affecting adipose tissue, liver, and muscle." (PMID 39195507, 2024). "A recent cross-sectional study also reported that cannabis consumption was linked to lower fasting insulin levels and a reduced risk of insulin resistance, as evidenced by lower HOMA-IR values." (PMID 38911246, 2024). "In fact, hyperglycemia is a possible risk factor for the development of AD, as well as low insulin response, i.e., insulin resistance." (PMID 39768255, 2024). "Increased lean mass was associated with increased fasting insulin and insulin resistance among participants who were overweight/obese but with decreased insulin resistance in normal-weight participants." (PMID 38173399, 2024). "Elevated FFAs contribute to insulin resistance caused by impaired insulin signaling and increased inflammation; additionally, cortisol inhibits glucose uptake in peripheral tissues and further contributes to insulin resistance." (PMID 38999025, 2024).
Insulin resistance (continued). "After multivariable adjustment, glucose tolerance, insulin resistance and insulin sensitivity are significantly and independently associated with global thickness of two distinct retinal bands, i.e. ONL and MZ." (PMID 38431705, 2024). "T2DM or adult-onset diabetes is non-insulin-dependent DM (NIDDM) and is characterized by two main insulin-related irregularities, such as insulin resistance and insulin deficiency due to the dysfunction of pancreatic β-cells." (PMID 38672494, 2024). "Higher circulating IGFBP1 levels were associated with greater insulin sensitivity (lesser insulin resistance) at ~26 weeks gestation in the same cohort and in two additional pregnancy cohorts." (PMID 38627562, 2024). "We also examined the association of KITT(iv) with obesity, insulin resistance-related parameters, and the insulin dose required for glycemic control." (PMID 38905235, 2024). "High insulin levels caused by fructose-induced insulin resistance also raise IGF-1 levels, which foster cancer cell proliferation while suppressing apoptosis." (PMID 39310400, 2024). "It is characterized by insulin resistance, a poor ability of pancreatic β-cells to secrete insulin, and is associated with vascular complications (e.g., cardio- and cerebrovascular diseases)." (PMID 39458839, 2024). "Genetic and environmental factors contribute to the development of insulin resistance, specifically in mutations in genes that are associated with intracellular insulin signaling pathways." (PMID 38397072, 2024). "It is known that increased CD36-mediated fatty acid uptake and lipid accumulation precede the loss of insulin-stimulated glucose uptake and the associated development of insulin resistance." (PMID 39125700, 2024). "Our study marks an important step towards understanding the role of insulin signaling in cardiac diseases linked to insulin resistance." (PMID 39026321, 2024). "Of these, visceral fat is more clearly associated with insulin resistance, while subcutaneous fat has a protective effect on insulin sensitivity." (PMID 39090692, 2024). "The alterations in RBCs and hematocrit observed in this study are probably due to hyperinsulinemia and associated insulin resistance, where insulin plays a role in regulating erythropoiesis." (PMID 39858414, 2024). "Elevated FSG levels are frequently linked to insulin resistance, a condition in which the body’s cells fail to respond adequately to insulin, a hormone that regulates blood sugar." (PMID 39668394, 2024). "The role of galactose, high-fat diets, and oxidative stress in elevating blood glucose levels has been well documented, mainly due to their association with insulin resistance or impaired insulin secretion." (PMID 39765817, 2024). "Circadian cycle asynchrony contributes to the pathophysiology of type 2 diabetes, as down-regulation of circadian cycle genes is associated with insulin resistance, decreased insulin secretion, increased postprandial glucose, and elevated HbA1c levels." (PMID 38421977, 2024). "The weakening of the effects of insulin in skeletal muscle, adipose tissue, or liver cells is known as insulin resistance (IR), which is also defined as the state of aberrant blood glucose response linked to a specific insulin concentration." (PMID 39014458, 2024). "HOMA-IR is recognised as a diagnostic index for insulin resistance, where a higher concentration of fasting insulin to maintain a low fasting glucose results in a higher HOMA-IR value." (PMID 39062126, 2024). "NDUFC2 appears to be downregulated in the skeletal muscle cells of individuals with insulin resistance and is linked to insulin secretion in vivo." (PMID 38689208, 2024). "Supplementation with 480 mg/day resveratrol associated with significantly lower fasting insulin levels and insulin resistance, in addition to significantly decreased pocket depths." (PMID 39917650, 2024).